SRSF10 (serine and arginine rich splicing factor 10)
Diseases named in the same sentence as SRSF10 in open-access papers (continued):
Sharing a sentence is not in itself a finding about the gene and the disease.
preeclampsia (1 paper, 2025). Preeclampsia is a hypertensive disorder of pregnancy that is characterized by new-onset hypertension with proteinuria presenting after 20 weeks of gestation, and depending on mild or severe forms may initially present with severe headache, visual disturbances, and hyperreflexia. "Constructed a protein–protein interaction (PPI) network, identifying 10 hub genes, seven of which (HK2, SRSF10, SOD1, ERO1L, IRF3, MME, and SH3BP5) were strongly linked to preeclampsia." (PMID 40966654, 2025). "Further analysis of gene regulatory networks, including transcription factor–gene, gene–microRNA, and drug–gene interactions, revealed that seven hub genes (HK2, SRSF10, SOD1, ERO1L, IRF3, MME, and SH3BP5) were strongly associated with preeclampsia." (PMID 40966654, 2025).
prostate carcinoma (1 paper, 2022). A carcinoma that arises from epithelial cells of the prostate gland. "Notably, depletion of tNASP reportedly inhibits proliferation in prostate cancer PC-3 cells and renal cell carcinoma cells, echoing the cell cycle defects of Srsf10-cKO spermatogonia." (PMID 36355419, 2022).
psoriasis (1 paper, 2023). An autoimmune condition characterized by red, well-delineated plaques with silvery scales that are usually on the extensor surfaces and scalp. "A psoriasis-prone variant of TRAF3IP2-AS1, A4165G (rs13210247), was identified as a gain-of-function mutant with enhanced binding affinity to SRSF10." (PMID 37310201, 2023). "Therefore, TRAF3IP2-AS1 and SRSF10 May be therapeutic targets for psoriasis." (PMID 37310201, 2023). "Interestingly, the antisense of TRAF3IP2, which is an lncRNA termed TRAF3IP2-AS1, is also vital in regulating psoriasis, especially in inhibiting the IL−17A-induced activation of NF-κB signalling and MAPK signalling by binding to SRSF10 and thereby blocking the subsequent recruitment of ACT1." (PMID 37310201, 2023).
sarcoma (1 paper, 2021). A usually aggressive malignant neoplasm of the soft tissue or bone. "Among them, high expression levels of SMARCC1, SRSF10, PRPF38A, JARID2, GNAI3, miR-301a-3p, miR-106b-5p, miRNA-130b-3p, miR-423-3p and LINC01296 and low expression levels of ARF3 and PRKCB were associated with shorter overall survival in sarcomas." (PMID 33653335, 2021). "Among the seven survival-associated mRNAs, the high expression levels of SMARCC1, SRSF10, PRPF38A, JARID2 and GNAI3 were significantly associated with shorter overall survival in sarcomas (P = 0.0018, P = 0.037, P = 0.0058, P = 0.0093, and P = 0.0234, respectively)." (PMID 33653335, 2021).
triple-negative breast carcinoma (1 paper, 2024). An invasive breast carcinoma which is negative for expression of estrogen receptor (ER), progesterone receptor (PR), and human epidermal growth factor receptor 2 (HER2). "MDM4, whose splicing was previously shown to be regulated by SRSF10, and affected by GPS167, may also be important for metastasis since its knockdown reduces circulating tumor cells in triple-negative breast cancer without affecting proliferation." (PMID 38753413, 2024).
type-2 diabetes (1 paper, 2022). "Notably, the SRSF10 locus has been recently associated with type-2 diabetes adjusted for body mass index in east Asian individuals, but the molecular basis of this association has not been established." (PMID 35293570, 2022).
viral infections (1 paper, 2022). "Furthermore, the SRSF10 protein is important for neurological processes and responses to viral infections, and abnormalities of both these groups of processes are evident in MPS." (PMID 35456399, 2022).
tumor (18 papers, 2009 to 2026). "We observed reduced tumor growth in mice bearing SRSF10 deficiency tumors compared with control mice." (PMID 40701249, 2025). "Moreover, the tumors treated with cisplatin or bearing deficiency of CK1ε and SRSF10 had decreased protein level of Bcl-xL and reduced tumor cell density." (PMID 40701249, 2025). "Moreover, SRSF10 expression was negatively associated to tumor diameter." (PMID 38049848, 2023). "Accordingly, not only SRSF10 expression but that of the other four candidates displayed associations with important diagnostic parameters, such as incidental diagnosis, detection of malignancy using fine needle aspiration or tumor size, highlighting their potential as diagnostic biomarkers." (PMID 38049848, 2023). "Serine/arginine-rich splicing factor-10 (SRSF10)-induced lactate overproduction within tumor cells was also found to be involved in M1-to-M2 switching." (PMID 40500404, 2025). "In A549 xenograft tumor model, SRSF10 knockdown combined with SR3029 administration synergistically inhibited tumor growth, accompanied with decreased protein level of Bcl-xL." (PMID 40701249, 2025). "Several upregulated proteins in the reintervention group, including SNRPD1, SRSF10, SWAP-70, and PSMB1, are associated with tumor progression in other cancer types." (PMID 38157275, 2024). "To investigate the function of SRSF10 in vivo, we determined that the stable knockdown of tumor SRSF10 significantly delayed the tumorigenesis of both Hep3B and HCCLM3 cells in xenograft mouse models." (PMID 35296659, 2022). "In the current study, SRSF10 expression was detected in liver tissues of HCC patients, and the correlation of SRSF10 levels with tumor phenotypes was analyzed." (PMID 36539837, 2022). "Analysis of the multiple Gene Expression Omnibus (GSE124535, normal vs. tumor) and TCGA datasets (normal vs. tumor) revealed significantly enriched SRSF10 in HCC versus normal tissue." (PMID 36539837, 2022). "In order to evaluate if these extra-tumoral staining were due to infiltrating tumor cells, we utilized another antibody recognizing a human nuclear protein (SRSF10)." (PMID 34203762, 2021). "Further, to support our preliminary analysis, we analyzed the HNC profiles available in the Oncomine and observed the upregulation of SRSF10 in tumor tissues as compared to normal tissue obtained from the HNC patients." (PMID 34616729, 2021). "Utilizing multiple mouse models, we confirmed that SRSF10 ablation with a selective inhibitor 1C8 robustly inhibits GC growth and enhances CD8+ T-cell infiltration via CCL2-mediated reprogramming of tumor-associated macrophages (TAMs)." (PMID 42020371, 2026). "Histological analyses revealed that either SRSF10 deficiency or SR3029 treatment reduced tumor cell density, and the combination of SRSF10 deficiency and SR3029 treatment exerted strongest inhibitory effect on tumor cell density." (PMID 40701249, 2025). "SRSF10-knockdown A549 cells and the parental counterpart were subcutaneously injected into the right back of the mice (5 × 106 cells per mouse, five mice per group), the growth of tumor was observed and the size of tumor was measured every 2 days." (PMID 40701249, 2025). "Moreover, SRSF10 facilitates tumor progression by promoting M2 macrophage polarization, thereby reducing CD8+ T cells infiltration and fostering an immunosuppressive tumor microenvironment." (PMID 41152975, 2025). "The analysis further indicated that three m6A readers are differentially expressed in the mCRPC tissues, where the YTHDF2 gene showed significant upregulation, while the NUDT21 and SRSF10 genes showed significant downregulation in mCRPC compared to both the localized tumor and normal tissues." (PMID 38610981, 2024).
tumor (continued). "In the case of SRSF10, the tumor tissue showed a mild staining at the cytoplasmic level that contrasted with an intense and uniform staining at the nuclear level, whereas adjacent non-tumor tissue showed very weak staining in the cytoplasm and weak and diffuse staining in the nuclear compartment." (PMID 38049848, 2023). "Next, we validated these in silico analysis in the HNC tissue samples obtained from the HNC patients receiving treatment at the Bansal Hospital, Bhopal, and observed the increased SRSF10 level by immunoblotting in HNC patient’s tumor tissues as compared with the paired normal." (PMID 34616729, 2021). "Although a body of research studied the role of SRSF10 in the splicing process, the regulatory mechanisms underlying SRSF10 upregulation in the tumor are not very clear." (PMID 34616729, 2021). "C-Myc then promotes lactate-dependent expression of serine/arginine-rich splicing factor 10 (SRSF10), which induces alternative splicing of genes such as the apoptosis inhibitor, Bcl-x, and enhances tumour survival." (PMID 39282472, 2024). "To this end, since their expression was augmented in tumor tissue, we performed silencing experiments of NOVA1, PRPF8 and SRSF10 in UMC-11 and NCI-H727 cells, two distinct broadly used pulmonary carcinoid cell models." (PMID 38049848, 2023). "Specifically, the splicing machinery components KHDRBS1, NOVA1, PRPF8, SNW1, SRSF1, SRSF10 and SRSF9 were overexpressed in tumor tissue." (PMID 38049848, 2023). "Multiple clinicopathological parameters reveal that SRSF10 in the HCC tissues (n = 74) was highly correlated with the neoplastic grade (Edmondson-Steiner, P = 0.01) and tumor size (P < 0.001)." (PMID 36539837, 2022). "As for an impact on immune signaling, SRSF10 has recently been reported to inhibit the IFNα/IFNγ signaling pathway and suppress CD8+T cell infiltration, while its knockdown enhanced the anti-PD-L1-mediated anti-tumor activity." (PMID 38753413, 2024). "To date, the role of SRSF10 in different model systems has been shown but what leads to an increase in the expression of SRSF10 in tumor samples in comparison to normal is not yet clear." (PMID 34616729, 2021).
cancer (15 papers, 2011 to 2025). A tumor composed of atypical neoplastic, often pleomorphic cells that invade other tissues. "We identified several cancer-associated splicing factors as G4 sensitisers, including SRSF10, HNRNPM and the known G4-interactor FUS, which is overexpressed in several cancers." (PMID 31287417, 2019). "Seven of the identified HGs (HK2, SRSF10, SOD1, ERO1L, IRF3, MME, and SH3BP5) were associated with PE and various carcinomas." (PMID 40966654, 2025). "Statistical analysis showed that SRSF10 was significantly up-regulated in the HNC cancer patient samples compared with the paired normal tissues." (PMID 34616729, 2021). "Together, these results suggest that SRSF10 promotes the cancer-specific isoforms of genes like PKM and BCLx thus play a crucial role in HNC." (PMID 34616729, 2021). "Consistent with this view, SRSF10 controls the alternative splicing of exon 5a in BCLAF1 in a variety of cancer cell lines." (PMID 27851963, 2016). "Compounds like 1C8 and GPS167 that inhibit or modulate the activity of SRSF10 could therefore become useful therapeutics against aggressive forms of cancer." (PMID 38753413, 2024). "Given that both 1C8 and GPS167 affect SRSF10 phosphorylation, we hypothesized that investigating the effects of these two compounds would uncover shared pathways relevant to cancer progression." (PMID 38753413, 2024). "SRSF10 is highly expressed in many cancers and plays a cancer-promoting role." (PMID 36611187, 2023). "HPV16- and HPV18-positive cancers display increased SRSF10 (SRp38/SRrp40) expression which could be upregulated by E6E7 via E2F1 transcriptional activation." (PMID 35563334, 2022). "Finally, we investigated the cancer-promoting mechanism of SRSF10 in AML." (PMID 36611187, 2023). "We observed that SRSF10 plays a crucial role in HNC tumorigenesis by affecting the pro-death, pro-survical splice variants of BCL2L1 (BCL2 Like 1: BCLx: Apoptosis Regulator) and the two splice variants of PKM (Pyruvate kinase M), PKM1 normal isoform to PKM2 cancer-specific isoform." (PMID 34616729, 2021). "Recently update on SRSF10 and TXNDC5 have indicated their diverse and signaling regulatory roles in cancers." (PMID 35296659, 2022). "Host RNA splicing factor SR proteins, including SRSF1(ASF/SF2), SRSF2 (SC35), SRSF3 (SRp20), and SRSF10 (SRp38/SRrp40), are also upregulated in HPV-positive cervical precancer lesions and cancer tissues." (PMID 35563334, 2022). "We depleted the SRSF10 in HNC cells, where we observed the switch in splicing from cancer-specific isoform to normal isoform in SRSF10 down-regulated cells in comparison to the control cells at the mRNA and protein level." (PMID 34616729, 2021). "Previous studies have demonstrated that most SRSFs were extensively dysregulated with oncogenic roles through regulating the AS of various cancer-related genes in many cancers such as lung (SRSF1, SRSF5), breast (SRSF3), colon (SRSF1, SRSF10), liver cancers (SRSF2), and glioma (SRSF1, SRSF3)." (PMID 37558679, 2023). "SRSF10 was slightly mutated (0.75%) only in UCEC, but not in other cancer types." (PMID 38015716, 2023). "Finally, we focused on the splicing factor SRSF10, a gene that plays an active tumor-promoting role in many cancers but whose expression has not been reported in AML." (PMID 36611187, 2023). "Thus, we hypothesized that SRSF10 regulates the PKM splicing favoring the PKM2 isoform, leading to the cancer progression via the Warburg effect." (PMID 34616729, 2021). "Further, to analyze the role of SRSF10 in PKM and BCLx pre-mRNA splicing, we examined the PKM and BCLx pre-mRNA-splicing pattern in SRSF10 depleted HNC cells and observed the splicing switch of PKM and BCLx gene from cancer-specific (PKM2 and BCLxL) isoform to normal isoform (PKM1 and BCLxs)." (PMID 34616729, 2021).
infection (2 papers, 2020 to 2023). The state of being infected such as from the introduction of a foreign agent such as serum, vaccine, antigenic substance or organism. "In dHepaRG cells, a reproducible increase of HBV RNA could be observed following SRSF10 KD even if at a lower level as compared to cells in which the KD was performed before infection." (PMID 33180834, 2020). "As previously observed in cells transfected before infection, SRSF10 KD also increased cccDNA level suggesting that, in this cell type, SRSF10 may modulate cccDNA recycling and /or stability in addition to its effect on HBV RNAs." (PMID 33180834, 2020). "To further clarify the biological role of SRSF10 in the development of AML, we obtained cDNA containing SRSF10 sequence and a plasmid targeting shRNA, which were packaged with lentivirus, followed by infection of the AML cell line THP-1." (PMID 36611187, 2023).
SRSF10 also shares sentences with these, for which no sentence is quoted: acute lymphoblastic leukemia (1 paper); cervical tumour (1); cholangiocarcinoma (1); gastric cancer (1); liver cancer (1); neuroblastoma (1); Nonalcoholic fatty liver disease (1); ovarian carcinoma (1); renal cell carcinoma (1); rheumatoid arthritis (1).